IGF1R (insulin like growth factor 1 receptor)
Diseases named in the same sentence as IGF1R in open-access papers (continued):
Sharing a sentence is not in itself a finding about the gene and the disease.
cancer (continued). "KEGG enrichment analysis identified crucial nodes in the signaling pathways associated with cancer development, including VEGFA, INS, IGF1R, and INSR." (PMID 38305809, 2024). "The correlation between elevated levels of IGF-1R pathway signaling and cancer is significantly positive." (PMID 38665430, 2024). "The major candidates for evaluation as anti-cancer agents are, anti-IGF-1R monoclonal antibodies, small molecule tyrosine kinase inhibitors and inhibitors of IGF ligands and their isoforms." (PMID 39273251, 2024). "For instance, in cancer, the role of IGF-1R is highly dependent on the cancer type, specifically which tissues and cells are affected." (PMID 39638246, 2024). "Various studies have demonstrated that IGF-1R signaling induces EMT through multiple mechanisms in different cancers, including breast, prostate, and lung." (PMID 38540176, 2024). "All these mechanisms work together to synergistically enhance the therapeutic effectiveness of IGF-1R-targeted therapies in cancer treatment." (PMID 38540176, 2024). "In many cancers, there were overexpressions of IGF-1R and increased IGF-1R tyrosine kinase activity." (PMID 40777947, 2024). "These collective endeavors highlight the potential to use IGF-1R inhibition as a potent anti-cancer therapy, mainly when employed in conjunction with complementary treatment modalities." (PMID 38540176, 2024). "Collectively, these pre-clinical and clinical results strongly support the development of therapeutic strategies targeting the IGF1/IGF1R axis to boost anti-cancer immunity and to potentially improve the efficacy of current immuno-oncotherapeutic approaches." (PMID 38420122, 2024). "In this study, we investigated how cell adhesion controls IGF-1R location and activity in cancer cells and fibroblasts." (PMID 39608716, 2024). "Current research indicates that IGF-1R is highly expressed in various tumors and functions as an oncogene in the development and progression of cancer." (PMID 38715012, 2024). "Further translational efforts are required to determine if the benefits of dual treatment with an IR/IGF-1R inhibitor and chemotherapy observed in vitro can be achieved in patients with cancer." (PMID 38786030, 2024). "For example, MUFA-PLs have been demonstrated to enhance IGF1R and IR activity in several type of cancers." (PMID 38424041, 2024). "IGF-1R overexpression has been shown in other cancers, while the blockade of IGF-1R stimulation suppresses the expansion and spread of a broad range of malignancies." (PMID 39335147, 2024). "The insulin-like growth factor 1 receptor (IGF-1R) and its ligands (IGF-1 and IGF-2) are essential for cell, organ, and organismal growth, and are linked to cancer risk, cancer progression, and inflammation." (PMID 39608716, 2024). "Insulin receptor (IR) and insulin-like growth factor-1 (IGF-1R) are both critical in the progression of cancer, particularly in tumorigenesis and the development of cancer drug resistance due to cross-talk between IGF-1R and IR signaling pathways." (PMID 39335147, 2024). "IGF-1R is known to be involved in carcinoma progression: it promotes tumor initiation and metastatic seeding, especially in lung cancer." (PMID 39766058, 2024). "Silibinin, a flavonolignan, enhances autophagy in carcinoma A431 cells by inhibiting the insulin-like growth factor 1 receptor (IGF-1R) pathway and upregulating Beclin 1 and ATG5 expression." (PMID 39371094, 2024). "IGF-1R inhibition has been widely investigated for various cancer treatments with numerous clinical trials." (PMID 37242543, 2023). "Insulin-like growth factor-1 receptor (IGF-1R) promotes cell proliferation and migration and inhibitsapoptosis, all of which can contribute to the development of cancers." (PMID 36698167, 2023).
cancer (continued). "Mechanistically, IGF1R blockade stimulated a STAT3-dependent increase in autocrine IGF2 production by cancer cells, which recruited macrophages and fibroblasts, leading to the production of CXCL8 and proangiogenetic and prometastatic actions." (PMID 36672737, 2023). "Considering the function of IGF1/IGF1R in cell differentiation, proliferation, and apoptosis, its activation is correlated with initiation, progression of cancer, and poor survival." (PMID 37284192, 2023). "IGF-1/IGF-1R signaling affects diverse biological processes in cancer cells, including promoting survival and renewal, inducing migration and spread, and promoting resistance to radiation and castration." (PMID 36831629, 2023). "On the other hand, unbalanced IGF/IGF-1R signaling can promote cancer cell proliferation and activate cancer reprogramming in tumor tissues, especially in the liver, by the activation of multiple cytokine pathways." (PMID 36831004, 2023). "Overall, the IGF1R gene is an important player in cancer pathogenesis and a promising target for cancer therapy development." (PMID 37744271, 2023). "Given its potent anti-apoptotic and pro-survival roles, and in view of its almost universal pattern of expression in most types of cancer, IGF1R has emerged as a promising molecular target in oncology." (PMID 37834331, 2023). "Nuclear transport of IGF-1R has been identified as an adverse prognostic factor in different cancers and is observed in pHGG." (PMID 37259440, 2023). "Previous work has identified the involvement of the insulin-like growth factor 1 receptor (IGF1R) receptor tyrosine kinase (RTK) in a wide range of cancers." (PMID 37686528, 2023). "BET protein action and the IGF system are connected as the IGF1R gene directly targets BRD4 in various cancer cell lines." (PMID 36831374, 2023). "One of the genes most significantly overexpressed in the poorest-prognosis CGS1 subtype was IGF1, a ligand for IGF1R that is a known potential therapeutic target for many cancers." (PMID 37674200, 2023). "This review summarizes the contribution of IGF-1/IGF-1R signaling to the development of PCa and highlights the relevance of IGF-1/IGF-1R signaling in potential cancer therapies." (PMID 36831629, 2023). "A phase I clinical trial of ridaforolimus in combination with anti-IGF1R mAb dalozumab also demonstrated clinical activity in advanced cancer." (PMID 36755926, 2023). "Although discouraging, these results promise that proper targeting of the IR and IGF-1R will inhibit cancer cell vitality and growth." (PMID 36831374, 2023). "BACH1 regulates cancer proliferation by targeting IGF1R and PTK2 and affecting angiogenesis and cell cycle." (PMID 37228820, 2023). "Patient-derived cancer cells were sorted using anti-NRP1 or anti-IGF1R antibodies and cultured in floating spheroid-forming conditions for CSC enrichment (left)." (PMID 37966117, 2023). "Dysregulation of the expression and function of IGF2 receptors, insulin receptor isoform A (IR-A), insulin growth factor receptor 1 (IGF1R), and their downstream signaling effectors drive cancer initiation and progression." (PMID 36672737, 2023). "IGF-1/IGF-1R signaling has been widely examined for its role in cancer progression through the regulation of cancer-stemness markers as well as EMT markers." (PMID 36765890, 2023). "Preclinical and clinical evidence shows that acute and chronic exercise interventions raise the expression of miR-133, which alters cancer progression by acting on oncogenes IGF-1R and EGFR." (PMID 36612320, 2023).
cancer (continued). "It has been demonstrated that NRF2 activation interacts with SP1, a potent transactivator of the IGF1R gene, thereby promoting the expression of IGF-1R and facilitating cancer progression." (PMID 37834454, 2023). "The underlying mechanism involves the modulation of cancer stemness, IGF-1R/p-IGF1R/OCT4, and metabolic changes." (PMID 36765890, 2023). "As a matter of fact, alterations in the autocrine loops IGF-2/IGF-1R often occur in human cancer, leading to the overactivation of the PI3K/AKT signaling pathway, which is responsible for impairment in cell proliferation and apoptosis." (PMID 36901760, 2023). "Collectively, the results in present study strongly suggest that monensin is probably to exert anti-cancer activity by inhibiting the IGF1R signaling pathway via IGF1 increase." (PMID 36896461, 2023). "On the other hand, IGF-1/IGF-1R signaling has been recognized as playing a role in the development of cancer." (PMID 36891560, 2023). "We also observed re-expression of CCND2, CD82 and IGF1R in three out of four models, which was already described after azacytidine treatment in several cancers." (PMID 36765607, 2023). "Short-chain oligosaccharides (HS06) can enter a unique pocket in the IGF-1R ectodomain and compete with the natural cognate ligand IGF-1, thereby blocking the physiological processes mediated by IGF-1R and exerting anti-cancer effects." (PMID 37765064, 2023). "The role of IGF-1 signaling is mainly explained by the mechanisms of increased proliferation, migration and cell survival via irradiated CAFs, which activate IGF-1R/AKT/mTOR signaling in cancer cells." (PMID 36835075, 2023). "The insulin receptor (INSR) gene has been studied less extensively in cancer, even though its protein can bind the same ligands as the IGF1R." (PMID 38136416, 2023). "On the other hand, excess signaling through IGF1R can contribute to gigantism and cancer progression." (PMID 36548088, 2023). "The IGF-I signal in cancer cells relies on the expression of both the IGF-IR and the IGF1R/IR hybrid." (PMID 38255147, 2023). "Although the results of clinical trials of anti-IGF1R monoclonal antibodies and IGF-1R inhibitors have been mostly disappointing in unselected cancer patients, some patients benefit from anti-IGF1R therapy in these failed studies." (PMID 36774408, 2023). "Studies have shown that blocking the IGF1R pathway can inhibit cancer cell growth and promote apoptosis." (PMID 37744271, 2023). "As a transmembrane tyrosine kinase, Insulin-like growth factor-1 receptor (IGF1R) vitally participates in the regulation of cell growth and differentiation, and its dysregulation contributes to oncogenic transformation and cancer development." (PMID 37777542, 2023). "IR overexpression in cancers makes the IGF1R, IR, and the pathways they activate promising therapeutic targets." (PMID 36831374, 2023). "In conclusion, more translational research is needed to reveal the underlying mechanisms between the genetic variation in IGF1R and INSR in the context of fasting and clinical response in cancer." (PMID 38136416, 2023). "IGF-1/IGF-1R is a candidate autocrine/paracrine ligand-receptor pair that promotes cancer progenitor cell and mature cancer cell resistance to castration." (PMID 36831629, 2023). "In normal cells, the IGF1R signaling pathway is tightly regulated, but in cancer cells, it can become dysregulated, leading to uncontrolled cell growth and proliferation." (PMID 37744271, 2023). "Recently, exosome-mediated transfer of non-coding RNA has been verified to be involved in angiogenesis, cell proliferation and fibrosis, and carcinoma progression by regulating IGF1R." (PMID 38037065, 2023). "Our results also showed that low levels of IGF1 induce the expression of miR-15b in M6 cells (carcinoma), and miR-15b inhibition induced the expression of Igf1r, suggesting a possible feedback loop between IGF1/IGF1R and miR-15b." (PMID 37686596, 2023).
cancer (continued). "Insulin-like growth factor 1 receptor (IGF1R) acts at the crossroad between immunity and cancer, being an attractive therapeutic target in these areas." (PMID 36105797, 2022). "IGF1R activation in tumors can promote tumorigenesis, maintain the transformed phenotype, promote cancer progression, stimulate cell migration, epithelial-mesenchymal transformation, and chemotherapy resistance." (PMID 35651701, 2022). "In this review, we discuss the clinical relevance of therapeutic strategies that target the IGF/IGF-1R axis in multiple malignant tumors and the applicability of IGF/IGF-1R axis strategies to improve stem cell-based therapies for human diseases." (PMID 36233084, 2022). "Based on the specificity of IGF1R, we reviewed the literature and found that examinations of various tumors showed abundant expression of IGF1R, which suggests that upregulation of the IGF1R gene constitutes a common paradigm in different types of cancer." (PMID 38091511, 2022). "Nuclear IGF-1R is overexpressed in cancer cells and high levels inversely correlate with survival of cancer patients." (PMID 35887358, 2022). "The inherent anti-apoptotic activity of the IGF1R confers upon receptor-expressing cells enhanced survivability, a fundamental property of cancer cells." (PMID 36479090, 2022). "In another study, it was seen that melatonin treatment of breast cancer cells causes reduced VEGF-A protein expression and increased IGFBP-3, IGFPB-6, IGF-1, IGF-1R proteins in those cells and results in suppression of cancer cell growth." (PMID 36581900, 2022). "The expression of both IGF1 and IGF-1R within the same cancer confirms the existence of an autocrine–paracrine signalling loop of RCC cell stimulation." (PMID 35328822, 2022). "Novel transmembrane proteins such as IGF-1R is known for their role in modulating cancer stemness and resistance to chemotherapy." (PMID 35941699, 2022). "This review summarizes the contribution of IGFs/IGF-1R signaling in the treatment of cancer and stem cells and also highlights the relevance of IGFs/IGF-1R signaling in potential strategies for cancer or stem cell-based therapies, respectively." (PMID 36233084, 2022). "The dynamic balance between IR and IGF-1receptor greatly enhances cancer cells’ ability to endure chemotherapies targeting IGF-1R and cancer cell apoptosis." (PMID 35252207, 2022). "As malignant tumor growth rely on increased bioenergetic demand, the impact of GRK2 on IGF1R signaling warrants further inverstigation as it holds pharmacological promise to various cancer types." (PMID 35430346, 2022). "Expression levels of IGF1R correlate with Fuhrman grading in ccRCC tissues, and high IGF1R expression confers a significant reduction in cancer specific survival." (PMID 36289686, 2022). "This drug, commercially known as linsitinib, is an orally bioavailable, selective, dual IR/IGF1R inhibitor which has been tested clinically in different cancers." (PMID 35574033, 2022). "At the same time, previous studies have confirmed that the downstream genes of LNC00324 can induce cancer cells to develop resistance to chemotherapy, including IGF-1R, AKT1, and STAT3." (PMID 36620587, 2022). "Accordingly, data obtained from cBioPortal cancer database showed increased gene amplification frequency, mRNA expression and copy number values of IGF1R in NSCLC patient tissue samples." (PMID 35688943, 2022). "In cancer cells, IGF1R participates in the control of cellular processes ranging from proliferation and migration to drug resistance." (PMID 36105797, 2022). "Recently, IGF1R has been shown to facilitate epithelial-mesenchymal transition and cancer stem cell properties via Akt activation." (PMID 35651701, 2022). "Comparing the proteins of exosomes from chemotherapy-induced dormant cancer cells and untreated cancer cells, we identified IGF-1R signaling activation as the main mechanism of how cancer cell exosomes educate BMSCs." (PMID 36568212, 2022).
cancer (continued). "The important role of the insulin-like growth factor 1 receptor (IGF-1R) in malignant tumors has been fully established." (PMID 36497233, 2022). "Reduced expression of both reporter proteins and endogenous expressions of stathmin-1 (STMN1) and insulin-like growth factor-1 receptor (IGF-1R) functionally inhibit the proliferation of these cancer cells." (PMID 35832790, 2022). "Overall, data obtained from different studies included in the cBioPortal cancer database, showed an increased IGF1R amplification frequency with an average of 1.385%." (PMID 35688943, 2022). "IGF-1R signaling promotes cancer cell proliferation, survival, migration, angiogenesis, hypoxia response and metastasis, and contributes to resistance to anti-cancer therapies 9-12." (PMID 35401828, 2022). "Taken together, studies are in agreement with the notion that IGF1R expression and/or activation are fundamental pre-requisites for cancer development." (PMID 36479090, 2022). "Clinical and experimental evidence suggests strong potential for IGF-1-R antagonists to overcome resistance to anti-cancer chemotherapy drugs." (PMID 36017326, 2022). "The targeting and elimination of senescent cells in cancer therapy and age-related disorders have been suggested to be a potentially efficient method for improving lifespan in parallel with targeting IGF1R signaling." (PMID 36291127, 2022). "Fibroblasts and pancreatic stellate cells also use IGF-1R signaling to support tumorigenesis and cancer drug resistance." (PMID 36017326, 2022). "Transcriptional misregulation in cancer: a broad range of human cancer had been correlated with the overexpression of insulin receptors (IR) and IGF-1R." (PMID 35207564, 2022). "Since the IGFs/IGF-1R signaling is often dyseregulated in cancer development, it has been considered an attractive pharmacological target for solid tumors." (PMID 36233084, 2022). "The insulin-like growth factor receptor (IGF1R) pathway plays an important role in cancer progression." (PMID 36093095, 2022). "IGF-1R inhibition has received abundant attention over the last decade for multiple cancer types, with the first FDA IGF-1R inhibitor, teprotumumab, a monoclonal antibody indicated for autoimmune Graves’ orbitopathy, approved in 2022." (PMID 36497341, 2022). "The high degree of structural homology between the IR and IGF-1R makes selectively targeting either receptor in the treatment of IGF-II-dependent cancers very challenging." (PMID 35304516, 2022). "One previous study reported that insulin-like growth factor 1 receptor (IGF1R) was a downstream target of miR-99b-5p, and mediated the effect of miR-99b-5p on cancer progression." (PMID 35030978, 2022). "It is shown that anti-tumor activity of melatonin in prostate cancer is mediated by IGF pathway in such a way that IGFBP3 is upregulated but IGF1R is downregulated after treatment of cancer cells by melatonin." (PMID 36581900, 2022). "Disappointing in vivo effects of anticancer molecules mediating strong effects in vitro through IGF-1R silencing were observed, possibly due to cancer cell resistance mediated by compensatory mechanisms activating IGF-1R downstream targets." (PMID 36017326, 2022). "In recent decades, a large body of evidence has supported the key role of IGF-1R signaling in the transformation of cells, cancer cell proliferation, and cancer metastasis." (PMID 36142299, 2022). "A prior study has exhibited that elevated IGF1-R enhances proliferation and metastasis of cancer cells." (PMID 35964060, 2022). "By combining IGF1R inhibition with autophagy disruptive agents, autophagy can be blocked, which can lead to suppressing cancer cell proliferation and enhancing apoptosis." (PMID 35651701, 2022).